INS (insulin)
Diseases named in the same sentence as INS in open-access papers (continued):
Sharing a sentence is not in itself a finding about the gene and the disease.
Obesity (continued). "These compounds may reveal interesting therapeutic properties, such as attenuation of body weight gain and amelioration of glucose-insulin homeostasis in a mouse model of HFD-induced obesity after administration of THCA." (PMID 33498537, 2021). "Our observation that obesity and T2D result in reduced vasodilator responsiveness to both Ach and SNP is in line with previous data, suggesting that these insulin resistant states, especially T2D, derail not only endothelial function, but also smooth muscle responsiveness to NO." (PMID 34440242, 2021). "The high prevalence of prepartum obesity in French Guiana may partially explain the greater proportion of GDM patients treated with insulin relative to mainland France." (PMID 34093431, 2021). "Increased plasma vaspin levels might represent a compensatory mechanism to preserve insulin sensitivity and glucose tolerance, which are impaired in obesity." (PMID 34359881, 2021). "Similarly, the role of anti-obesity medications and insulin sensitizers was varied across included CPGs." (PMID 33839790, 2021). "Although promising, together these findings show how essential future studies are in order to more clearly define the role and mechanisms of GPR41 in insulin secretion, as well as the potential druggability of its agonists/antagonists to improve T2D and obesity-related metabolic abnormalities." (PMID 34497585, 2021). "Moreover, Clostridium cocleatum and Clostridium ramosume were differentially correlated with the obesity indexes; Clostridium cocleatum was closely associated with body and fat weights, adipocyte size, BF, HOMA-IR, glucose and insulin." (PMID 34660667, 2021). "CgA-knockout mice also exhibit enhanced insulin sensitivity despite obesity." (PMID 34204153, 2021). "Given the link between muscle mitochondrial coupling efficiency and obesity-related metabolic disturbance, it is necessary to measure whole-body expenditure, oxygen consumption, glucose tolerance test, insulin tolerance test, and hyperinsulinemic–euglycemic clamps." (PMID 34684660, 2021). "When no insulin treatment was given during pregnancy, the obesity group had a significantly higher risk of PPD than the lean group (aRR 1.27; 95% CI 1.17–1.39; p < 0.0001)." (PMID 33743677, 2021). "Treg cells play a protective role in insulin sensitivity and energy homeostasis in obesity." (PMID 35822048, 2021). "The main effects of insulin and leptin in states of obesity include sexually dimorphic alterations." (PMID 34084149, 2021). "Without insulin treatment in pregnancy, women with obesity had a significantly higher risk of PPD when compared to lean women." (PMID 33743677, 2021). "Therefore, a randomised controlled trial is now required to investigate the effects of short-term blackcurrant extract supplementation in individuals with lower insulin sensitivity, such as those with overweight or obesity." (PMID 32648022, 2021). "Collectively, PVAT plays a fundamental role in the modulation of vascular function in mouse models of hyperglycemia induced by blockade of insulin signaling, that was not linked to fat load or obesity, known previously to affect PVAT also in humans." (PMID 34207844, 2021). "Obesity-induced resistance to insulin is another suggested pathway." (PMID 34681126, 2021). "These preliminary findings point to an unsuspected potential role for ADH1B in adipocytes and the adipocyte response to insulin, which may be a factor in obesity and related metabolic disorders." (PMID 33479282, 2021). "Since it has been well documented that inflammation deteriorates systemic insulin sensitivity and obesity, we tested whether an inflammation-related response occurred in the liver of LKO mice." (PMID 34684470, 2021). "It is apparent that obesity has different impact on glycerol and fatty acid handling by insulin." (PMID 34321614, 2021).
Obesity (continued). "Importantly, miR-155 knockout mice are characterized by increased WAT browning and resistance to HFD-induced obesity, increased insulin sensitivity and a decreased adipose tissue concentration of inflammatory parameters." (PMID 34943849, 2021). "Moreover, researchers also have examined that obesity increase lipid profile and significantly impact on HbA1c level, as a result of insulin inactivity." (PMID 36962092, 2021). "The results of the study in general showed that HFD induces obesity, which is characterized with increased body weight, visceral fat mass, fasting insulin and triglyceride-glucose index and decreased insulin sensitivity with unaltered blood glucose when compared to the control group." (PMID 34556775, 2021). "Some reports have mentioned resistin as a factor that may represent a link between obesity and insulin dysregulation." (PMID 35011183, 2021). "This work aimed to determine whether 11βHSD1 equilibrium in metabolic tissues is regulated by insulin and obesity." (PMID 33270115, 2021). "In summary, our data suggest that the miRNAs that regulate insulin signalling, lipid profile and oxidative stress, and which we have identified in our population, play an essential role in protecting against metabolic disease in obesity." (PMID 33801145, 2021). "Importantly, the hereto reported function of tanycyte IR signalling to gate ARC neuronal responses is well in line with data on the regulation of brain insulin access and action in lean subjects and humans with obesity." (PMID 34931084, 2021). "The differential dysregulation of insulin action in these hypothalamic nuclei under HFD could indicate cooperation between these responses to drive obesity." (PMID 34201257, 2021). "While for people with overweight/obesity, duration of obesity may lead to compensatory adaptations to maintain insulin sensitivity." (PMID 35242104, 2021). "Increased insulin levels in obesity, a consequence of insulin resistance, may play an important role in shaping Tregs function." (PMID 35822048, 2021). "Insulin dysregulation may well represent a mediating mechanism in the obesity–depression relationship, and is highly influenced by environmental factors." (PMID 33681273, 2021). "Although several genome-wide association studies (GWAS) have reported genetic loci associated with circulating insulin levels, the number of GWAS on obesity-related cytokines and hormones other than insulin is limited and these GWAS have been conducted primarily in European ancestry populations." (PMID 34620218, 2021). "IR induced by obesity could lead to an elevated inflammatory state by disturbing the anti-inflammatory role of insulin." (PMID 34524974, 2021). "We report an influence of leptin levels on the association between obesity and insulin and NEFA in young children that is not observed in adolescents." (PMID 35071145, 2021). "Herein, we investigated if SIT could suppress obesity induced inflammation and improve insulin sensitivity in the adipose tissues of HFD and sucrose fed type 2 diabetic rats." (PMID 33917607, 2021). "Furthermore, NE showed to be a regulator of insulin signaling, and its deletion improved insulin sensitivity in a mouse model of obesity." (PMID 34957156, 2021). "For instance, obesity impairs insulin signaling and promotes the secretion of cytokines and adipokines that dysregulate the transduction of the Janus kinase (JAK)/signal transducer activator of transcription (STAT) pathway, an important modulator of insulin function and T-cell responses." (PMID 33808960, 2021). "Indeed, mild suppression of insulin secretion has been proven as a strategy for preventing and treating obesity." (PMID 34015524, 2021). "In addition, ADCY5 genetic variants have been associated with lower birth weight, gestational diabetes, and parameters of insulin sensitivity in children with obesity." (PMID 33919448, 2021).
Obesity (continued). "The main finding of the present study among Finns was that presence of the obesity risk allele rs17782313-C does not affect brain glucose uptake in conditions of insulin clamp, or in a smaller set of subjects studied both under fasting and clamp conditions." (PMID 33806715, 2021). "In humans, Cidea is positively correlated with insulin sensitivity and healthy obesity." (PMID 35178394, 2021). "Despite obesity being a predisposing factor for pancreatic β-cell dysfunction and loss, the mechanisms underlying its negative effect on insulin-secreting cells remain poorly understood." (PMID 34183666, 2021). "Targeting gut microbiota could improve insulin sensitivity, thereby regulating insulin-mediated lipid metabolism in adipocytes and improving host obesity." (PMID 34366839, 2021). "This suggests an added benefit to maintaining sufficient insulin levels in pregnancy beyond the requirement to regulate blood sugar among women with obesity, and may be a preventative measure against PPD in order to better support maternal care of offspring." (PMID 33743677, 2021). "According to a recessive model analysis, similar to our results, the minor allele of the Pro12Ala PPARγ2 polymorphism has been associated with insulin levels in healthy men without obesity." (PMID 34887761, 2021). "Thus, our data demonstrate that the PM diet exerts an early effect on hepatic fatty acid metabolism prior to the onset of obesity or changes in insulin sensitivity." (PMID 34099716, 2021). "In our study, we have analyzed the relationship of the common variant Pro12Ala in the human PPARγ2 gene with the presence of obesity and with insulin, HOMA and lipid profile in a representative sample of 6-to 8-year-old children free from the confounding factors associated with adults." (PMID 34887761, 2021). "Consensus upon definition of cardiometabolic risk (CMR) in children has not been reached, but adiposity, lipid profile, glycaemia, insulin level and blood pressure are common elements of the CMR cluster across studies and higher degrees of obesity are associated to an increase in metabolic risk." (PMID 33803348, 2021). "Correspondingly, individuals with obesity exhibit lower levels of antioxidants and higher levels of oxidative stress, which may also decrease insulin sensitivity and lead to insulin resistance." (PMID 32741068, 2021). "When no insulin treatment was given during pregnancy, mothers with obesity had a significantly higher risk of PPD than the lean group (aRR 1.27; 95% CI 1.17–1.39; p < 0.0001)." (PMID 33743677, 2021). "Leptin insensitivity.Protection against obesity, increases insulin sensitivity." (PMID 34502119, 2021). "For such animals, namely for animals with endogenous obesity, improving the results of hepatokines and thus improving insulin and glucose metabolism may be considered an optimal achievement." (PMID 33833309, 2021). "Interestingly, recent studies have suggested that obesity-induced low-grade inflammation impairs also the brain function and disturbs glucose sensing, insulin signaling and hypothalamic circulation in central nervous system." (PMID 33627179, 2021). "Preclinical testing of desHis1Glu9-glucagon and desHis1Glu9(Lys30PAL)-glucagon in HFF obese mice reversed obesity-driven hyperinsulinaemia and insulin resistance together with improvements in lipid profile, glucose tolerance and increased pancreatic insulin stores." (PMID 34093449, 2021). "Four proteins including C-peptide, insulin (INS), insulin-like growth factors (IGFs) and IGF-binding proteins (IGFBPs) are taken multiple biological roles in the insulin-IGF-1 axis, one of the potential biological mechanisms underlying the obesity-breast cancer connections." (PMID 33859244, 2021).
Obesity (continued). "The precise mechanism of the NAC action is still unclear, but it is known that the development of inflammation during obesity induced by an HFD is associated with increased oxidative stress, which also worsens insulin signaling and accelerates myocardial damage." (PMID 34684414, 2021). "Mitochondrial overactivation by substrate influx is a mechanism of insulin resistance in obesity." (PMID 34987473, 2021). "LKO mice are highly insulin sensitive and resistant to diet-induced obesity." (PMID 33718833, 2021). "Dysfunction of cytokines and hormones such as leptin, ghrelin, insulin, GLP-1, resistin, and visfatin has been implicated causally in the pathogenesis of obesity but also as a mediator between excess fat mass and insulin resistance, T2D, and cardiovascular disease." (PMID 34620218, 2021). "Remarkably, upon feeding with high-fat diet, mice with pre- and post-natal deletion of Rptor in OBs were protected from diet-induced obesity and exhibited improved glucose metabolism with lower fasting glucose and insulin levels, increased glucose tolerance and insulin sensitivity." (PMID 33551450, 2021). "It remains to be explored whether improved insulin sensitivity in obesity by exercise is specifically mediated by alleviation of excessive energy generation." (PMID 34278707, 2021). "However, in our study, the BCAA diet group showed the greatest degree of resistance to obesity and the highest insulin sensitivity." (PMID 33997711, 2021). "Moreover, insulin, an anabolic hormone to improve energy storage, is to increase appetite and weight gain, which contributed to obesity with inhibited lipolysis in adipose and muscle tissues." (PMID 34367067, 2021). "The PSG values worsened along with the increasing insulin resistance in children with simple obesity and patients with PWS treated with rhGH that may lead to a change in the patients’ care." (PMID 33670584, 2021). "However, when people with obesity (BMI > 30 kg/m2) ingested the same amount of glucose, their insulin levels rose for hours." (PMID 33922802, 2021). "The insulin/IGF-1 signaling pathway may be involved in modulation of intestine epithelium hemostasis following obesity." (PMID 33827616, 2021). "Two central endocrine pathways in obesity are those of insulin and leptin." (PMID 34211985, 2021). "This may also represent the need to store more energy to adapt to the obesity status of requiring more energy storage and, therefore, more insulin (and also more leptin, for which a resistance also develops during obesity)." (PMID 33450943, 2021). "Obesity triggers the expression and release of the pro-inflammatory cytokine TNFα from adipocytes and resident macrophages in adipose tissue, where it interferes with insulin signaling and triglyceride metabolism." (PMID 34686752, 2021). "An experimental study in mice fed a high-fat diet showed that alcohol increased insulin sensitivity by upregulating anti-insulin sensitivity genes and that obesity-related alterations in insulin sensitivity were combined with alterations in insulin sensitivity genes." (PMID 34496822, 2021). "Insulin normally suppresses hepatic gluconeogenic enzyme expression and stimulates muscle glucose uptake, and both actions are impaired in diet‐induced obesity, the metabolic syndrome, type 2 diabetes (DIO/MetS/T2DM)." (PMID 34766133, 2021). "Studies in animal models and humans that investigated intestinal immune cells, barrier function and/or inflammation in intestinal tissues together with effects on systemic glucose and/or insulin metabolism and/or weight gain during obesity and T2D were selected." (PMID 35145486, 2021). "Furthermore, complement dysregulation was most pronounced in metabolically unhealthy subjects and correlated with both obesity and insulin sensitivity." (PMID 32865246, 2021).
Obesity (continued). "Weight gain during childhood promoted by excess protein intake is the result of increased insulin-hyper aminoacidemia levels which, in turn, stimulates IGF-1 secretion, increasing later risks concerning obesity and associated diseases, reinforcing the requirement for strict IFs protein adjustments." (PMID 34836188, 2021). "Long-term exposure to HSD could induce numerous physiological changes in Drosophila including obesity, insulin resistance, activated immune response, disrupted ovarian function, and shortened lifespan." (PMID 35059137, 2021). "Several studies conducted on animal models demonstrated that metabolites of fatty acids interfere in decreasing insulin transduction at multiple levels, especially the decline in phosphorylation of Akt as a consequence of the development of obesity in heart tissue in rodents." (PMID 34684414, 2021). "Moreover, we also noted that people with T1DM and overweight/obesity required higher doses of insulin to achieve similar glycaemic control to those with normal BMI." (PMID 34530819, 2021). "This temporal sequencing (in which changes in fasting insulin precede changes in weight) is not consistent with the assertion that obesity causes NCDs and premature death by increasing levels of fasting insulin." (PMID 33710289, 2021). "Obesity impairs SAT adipogenesis and storage capacity to a greater extent in women of African ancestry compared to European ancestry, which correlates with reduced insulin sensitivity and increased risk for T2D." (PMID 33921645, 2021). "In conclusion, our study revealed that ML inulin treatment can improve the obesity‐related indexes, chronic inflammation, insulin sensitivity, energy metabolism and composition of gut microbiota in diet‐induced obese mice, indicating ML inulin as a natural alternative for anti‐obesity." (PMID 34262707, 2021). "The downregulation of NLRP3 inflammasome activity in NAG-1 Tg mice may confer resistance against diet-induced obesity and improve insulin sensitivity." (PMID 34294853, 2021). "European ancestry, obesity, plasma insulin level, and test status may be potential factors affecting the relationship between Trp64Arg and IR." (PMID 34512548, 2021). "Concisely, in the absence of obesity, adipose tissue macrophages represent 10–15 % of stromal cells and present markers associated with the maintenance of insulin sensitivity by the production of IL-10." (PMID 33183383, 2021). "Escalating insulin doses to achieve glycemic goals may also further compound weight gain, exacerbating obesity-related complications." (PMID 33828529, 2021). "These species influenced the differentiation of the regulatory T cells, a substantial source of Il-10, an anti-inflammatory cytokine which presents anti-obesity actions by suppressing adipocyte energy expenditure, thermogenesis and by reducing insulin resistance." (PMID 34574159, 2021). "Also, with aging and obesity (especially abdominal obesity), insulin sensitivity gradually decreases in skeletal muscle and adipocytes, increasing serum glucose levels and promoting ER overload and Os." (PMID 34676021, 2021). "Decreased hepatic clearance of insulin might also provoke hyperinsulinemia, especially in horses with obesity and IR, since more than 70% of the insulin secreted in the pancreatic beta cells is normally cleared from the portal blood by the liver." (PMID 34947937, 2021). "However, as obesity progresses, adiponectin, an adipocytokine that exhibits beneficial functions, such as insulin sensitivity and vasoprotective effects, decreases." (PMID 33924369, 2021). "These metabolic alterations, including the rising systemic insulin resistance, increased plasma leptin levels, and obesity may impair vascular function in large vessels only in a longer treatment model." (PMID 33791074, 2021).